RERE-AS1 (RERE antisense RNA 1)
Gene: Long non-coding RNA gene on chromosome 1 (8,424,645 to 8,435,013, forward strand). Ensembl gene ENSG00000232912.
Diseases named in the same sentence as RERE-AS1 in open-access papers:
RERE-AS1 is named in the same sentence as 1 disease in open-access papers, as found by Europe PMC text mining. Sharing a sentence is not in itself a finding about the gene and the disease. The quoted sentences say what the papers report.
tumor (1 paper, 2022). "Moreover, the expression levels of RERE-AS1 (p < 0.05), TFAP2A-AS1 (p < 0.01), and MIR302CHG (p < 0.05) varied according to tumor stage (stage I, II, III, and IV), COL4A2-AS1, RERE-AS1, NDUFA6-DT, and MIR302CHG varied according to T stage (T1, T2, T3, and T4)." (PMID 36313442, 2022).